RBM43 (RNA binding motif protein 43)
Synonyms: C2orf38; FLJ45645
Tractability: PROTAC: ubiquitination databases record sites on it.
Gene: Protein-coding gene on chromosome 2 (151,247,940 to 151,261,863, reverse strand). Ensembl gene ENSG00000184898.
Subcellular location (Human Protein Atlas): Nucleoli; Nucleoplasm
Gene Ontology:
Molecular function: protein binding; nucleic acid binding; RNA binding
Genetic constraint (gnomAD): Loss-of-function variants: 9 observed, 5.15 expected, observed/expected ratio (o/e) 1.75, 90% interval 0.95 to 1.95. That is too few expected variants to judge how well the gene tolerates losing a copy. Missense variants: 306 observed, 373.43 expected, observed/expected ratio (o/e) 0.82, 90% interval 0.75 to 0.9. Synonymous variants: 129 observed, 139.77 expected, observed/expected ratio (o/e) 0.92, 90% interval 0.8 to 1.07.
Homologues: Orthologues: chimpanzee RBM43 (98% identical), macaque RBM43 (92% identical), rabbit RBM43 (69% identical), guinea pig RBM43 (67% identical), rat Rbm43 (57% identical), mouse Rbm43 (56% identical). Paralogues in human: NMI (13% identical), IFI35 (11% identical).
Diseases named in the same sentence as RBM43 in open-access papers:
RBM43 is named in the same sentence as 13 diseases in open-access papers, as found by Europe PMC text mining. Sharing a sentence is not in itself a finding about the gene and the disease. The quoted sentences say what the papers report.
hepatocellular carcinoma (5 papers, 2021 to 2024). A malignant tumor that arises from hepatocytes. "Previous studies showed that CCNB1 was upregulated to promote proliferation of hepatocellular carcinoma via decreased its negative regulators, at least including RNA-binding motif protein 43 (RBM43), miR-199a-3p, or miR-144." (PMID 35078445, 2022). "The overexpression of RBM43 can inhibit the proliferation of hepatocellular carcinoma cells, and decreased the growth of transplanted tumors in vivo through modulation of cyclin B1 expression." (PMID 34531901, 2021). "The study found that RBM43 was significantly downregulated and its low expression was correlated with poor prognosis in hepatocellular carcinoma (HCC)." (PMID 34398362, 2021). "RBM43, a member of the RNA binding protein family, was verified to be considerably down-regulated in hepatocellular carcinoma (HCC), indicating poor prognosis in HCC patients." (PMID 39104422, 2024). "For instance, RNA-binding protein Nova1 and NELFE promote cancer growth in hepatocellular carcinoma (HCC) cells, whereas RBM47 and RBM43 have been shown to suppress HCC growth." (PMID 34434291, 2021).
liver cancer (2 papers, 2021 to 2024). An epithelial or non-epithelial malignant neoplasm that arises from the liver. "When we dissected mice after natural death with liver cancer induced by diethylnitrosamine and carbon tetrachloride, we found that compared with wild-type mice, more Rbm43-deficient mice developed ascites and metastatic lesions." (PMID 39104422, 2024). "Additionally, Rbm43-deficient mice with liver cancer also developed more metastatic nodules, which were dispersed around the surface of the large liver, lung, and kidney in comparison to wild-type mice." (PMID 39104422, 2024). "RNA-binding motif protein 43 (RBM43) was reported to be a tumor suppressor and correlated with poor prognosis in liver cancer." (PMID 34531901, 2021).
Barrett esophagus (1 paper, 2021). Esophageal lesion lined with columnar metaplastic epithelium which is flat or villiform. "Some previous studies have revealed that RBM43 acts as a genetic factor that contributes to type 2 diabetes (T2DM), endometriosis, esophageal adenocarcinoma (EA), and Barrett’s esophagus (BE)." (PMID 34398362, 2021).
esophageal squamous cell carcinoma (1 paper, 2021). Esophageal squamous cell carcinoma (ESCC) is a type of esophageal carcinoma (EC) that can affect any part of the esophagus, but is usually located in the upper or middle third. "However, the role of RNA-binding motif protein 43 (RBM43) in esophageal squamous cell carcinoma (ESCC) has not been reported so far." (PMID 34398362, 2021).
tumor (5 papers, 2020 to 2024). "The univariate analysis showed that the following parameters were significantly associated with OS: RBM43 expression, tumor status, nodal status (p = 0.001, p = 0.016 and p < 0.001, respectively)." (PMID 34398362, 2021). "In this study, we discovered that RBM43 protein levels were significantly increased in ESCC compared with the matched adjacent non-tumor tissues." (PMID 34398362, 2021). "The results demonstrated that RBM43 expression, tumor status and nodal status were independent prognostic factors for ESCC (p = 0.012, p = 0.029 and p < 0.001, respectively)." (PMID 34398362, 2021). "Overexpression of RBM43 suppressed cell proliferation in culture and resulted in the growth arrest of tumor xenografts." (PMID 34804951, 2021). "Furthermore, the prognostic value of RBM43 expression in different subgroups of ESCC patients was examined according to the 8th edition of the TNM (tumor, node, metastasis) classification." (PMID 34398362, 2021). "Moreover, further study would be necessary to determine the significance of various RBM43 staining patterns among tumor and stromal cells." (PMID 34398362, 2021). "Compared with our study, the opposite conclusion may be due to tumor heterogeneity and the complexity of RBM43 functions." (PMID 34398362, 2021). "In addition, we have found that RBM43 protein can also be expressed in stromal cells within the tumor microenvironment (TME)." (PMID 34398362, 2021). "RBM43 acted as a tumor suppressor that modulated CCNB1 expression to regulate the cell cycle, providing sufficient evidence for the significance of RBM43 in HCC." (PMID 39104422, 2024). "The analysis of IRS showed that RBM43 was commonly upregulated in ESCC issues, compared with adjacent non-tumor tissues (p < 0.0001)." (PMID 34398362, 2021). "However, in light of the abundance and complexity of RBM43 expression patterns within ESCC cells and the corresponding stroma, we have chosen to focus the discussion on expression of RBM43 in tumor cells." (PMID 34398362, 2021). "Furthermore, high expression levels of RBM43 were closely correlated with age and N categories, however, not with sex, tumor location, histological grade, pT status or TNM stage of patients with ESCC." (PMID 34398362, 2021). "The results of IHC staining revealed that the expression of RBM43 protein was predominantly localized to cytoplasm of ESCC tissues, whereas no or weak staining was observed in adjacent non-tumor tissues." (PMID 34398362, 2021).
cancer (1 paper, 2021). A tumor composed of atypical neoplastic, often pleomorphic cells that invade other tissues. "The number of studies reporting the role of RBM43 in cancer is very limited and, interestingly, the existing study that is available shows contradictory results." (PMID 34398362, 2021). "However, the main limitation of the study was the absence of further research to determine how RBM43 plays cancer-promoting roles in ESCC and the exact underlying mechanisms." (PMID 34398362, 2021).
infection (1 paper, 2024). The state of being infected such as from the introduction of a foreign agent such as serum, vaccine, antigenic substance or organism. "To investigate the effect of RBM43 on HCC metastasis further, we constructed RBM43-deficient HepG2 and QGY-7703 cells through CRISPR-Cas9 technology and successfully reconstituted RBM43 in knockdown HCC cell lines by lentivirus infection." (PMID 39104422, 2024).
RBM43 also shares sentences with these, for which no sentence is quoted: asthma (1 paper); breast carcinoma (1); colon cancer (1); Diabetes (1); esophageal adenocarcinoma (1); glioma (1).